VDR (vitamin D receptor)
Diseases named in the same sentence as VDR in open-access papers (continued):
Sharing a sentence is not in itself a finding about the gene and the disease.
vaginal cancer (1 paper, 2017). A primary or metastatic malignant neoplasm involving the vagina. "In this review, we shed light on the role of vitamin D and VDR in endometrial, ovarian, cervical, vulvar and vaginal cancers." (PMID 29113037, 2017). "A systematic search was done for: “vitamin D” or “vitamin D receptor” in combination with “endometrial, ovarian, cervical, vulvar and vaginal cancer/tumor,” identifying 200 articles." (PMID 29113037, 2017). "In this review, we systematically analyzed the effect of vitamin D and the vitamin D receptor on endometrial, ovarian, cervical, vulvar and vaginal cancer." (PMID 29113037, 2017). "The same applies to research on the vitamin D receptor in vaginal cancer." (PMID 29113037, 2017). "Although there is limited knowledge on the role of the VDR/RXR on the survival of endometrial, cervical, vulvar or vaginal cancer patients, some studies showed that both receptors influence survival." (PMID 29113037, 2017).
vaginal infection (1 paper, 2025). "Vitamin D supplementation might be extremely useful in lowering the host susceptibility to vaginal infections by lowering VDR placental expression." (PMID 40243431, 2025). "This research aimed to investigate how different types of vaginal infections during pregnancy alter the expression of VDR, CD44, OPN, and COX-2, thereby contributing to structural and functional changes in the placenta." (PMID 40243431, 2025). "The tissue samples of the vaginal infection-free control group exhibited similar VDR expression levels to women with Candida spp." (PMID 40243431, 2025). "We detected variability in the expression of molecules involved in placental adhesion, angiogenesis, migration, differentiation, and immune modulation (VDR, CD44, OPN, and COX-2) in different pathogenic vaginal infections." (PMID 40243431, 2025). "Our results suggest that pregnant women have a 1.67 increased risk of experiencing a vaginal infection if they are CD44-negative, a 1.102 increased risk of experiencing a vaginal infection if they are VDR-negative, and a 2.933 increased risk of having a vaginal infection if they are OPN-positive." (PMID 40243431, 2025). "VDR, CD44, and OPN had increased placental expression in GBS and Ureaplasma urealyticum vaginal infections; the opportunistic pathogenicity of both Escherichia coli and Candida spp." (PMID 40243431, 2025). "VDR was found to be positive in three-quarters of the vaginal infection cases, without significant difference between the two groups, with a p-value of 0.907." (PMID 40243431, 2025).
viral hepatitis (1 paper, 2019). An acute or chronic inflammation of the liver parenchyma caused by viruses. "Therefore, VDR is considered a powerful modulator of pathophysiological mechanisms in several human diseases such as cancers, metabolic disorders and infectious diseases, including viral hepatitis." (PMID 31864292, 2019).
Zinc deficiency (1 paper, 2022). A deficiency of the essential metal Zinc; an essential cofactor for many enzymes. "In a study on rats that were fed zinc-adequate or zinc-deficient diets, those with zinc-deficient diets showed significantly less intestinal mucosal expression of both VDR protein and CaBP protein and demonstrated that zinc deficiency has an effect on VDR expression, and functions." (PMID 35570853, 2022).
cancer (567 papers, 2005 to 2026). A tumor composed of atypical neoplastic, often pleomorphic cells that invade other tissues. "While tobacco smoking is the primary cause, genetic factors such as VDR polymorphisms can influence an individual's susceptibility to the disease, facilitating a more personalized approach to cancer risk assessment and prevention." (PMID 40356850, 2025). "Increased expression of VDR and ERβ1 has been linked to tumor suppression, highlighting their potential to impact cancer progression via various signaling pathways." (PMID 39968442, 2025). "The five studies collectively highlight the significant role of VDR polymorphisms on the risk of tobacco-related cancers." (PMID 40356850, 2025). "Significant associations have been identified between VDR polymorphisms and various cancers, including prostate (Fok1, Bsm1, Taq1), breast (Fok1, Bsm1, Taq1), colon-rectum (Fok1, Bsm1, Taq1), and cutaneouscancer (Fok1, Bsm1, Taq1)." (PMID 40356850, 2025). "In UC, VDR’s role is similar, as it helps control inflammation and maintain intestinal barrier integrity, reducing the risk of cancer development." (PMID 40791849, 2025). "Further studies are needed to understand how polymorphisms in the VDR and other vitamin D-related genes, as well as epigenetic changes, affect cancer risk." (PMID 40732958, 2025). "Case control studies (n = 5) showing effect of VDR polymorphisms on the risk of tobacco-related cancers." (PMID 40356850, 2025). "Activation of the VDR by vitamin D or other analogs causes cell cycle arrest in the G1/G0-phase for cancer cells." (PMID 41150758, 2025). "This is linked to changes in cancer cell differentiation and stemness, influenced by interactions of VDR-mediated signaling with other growth-promoting factors or microRNAs." (PMID 40332380, 2025). "The most common VDR gene polymorphisms, BsmI, FokI, and ApaI, are important in assessing survival in patients with cancer." (PMID 39861482, 2025). "There are controversial points in the literature regarding the role of vitamin D and vitamin D receptor gene variation in terms of any associated increased risk of developing cancer." (PMID 38125732, 2024). "The positive correlations of VDR expression with the expression of FAP (cancer-associated fibroblast marker), CD68 (macrophage marker), or CD15 (neutrophil marker) were experimentally verified in PTC tissues." (PMID 38639057, 2024). "The association between VDR polymorphisms and cancer susceptibility has been extensively investigated across various malignancies, including prostate, breast, colorectal, and skin cancer." (PMID 39683528, 2024). "The VDR gene (NCBI—Gene ID: 7421) encodes the vitamin D3 receptor, with downstream targets involving mineral metabolism, the immune response, and cancer." (PMID 39408801, 2024). "Increased VDR expression was associated with increased percentage of stromal or immune components in tumor microenvironment (TME) in 24 cancer types." (PMID 38639057, 2024). "VDR downregulation is associated with poor prognosis and cancer progression, while higher expression of VDR in epithelial colon cells correlates with better differentiation and prognosis." (PMID 39451780, 2024). "Haplotype analysis has revealed combinations of VDR polymorphisms associated with increased cancer risk, emphasizing the complex genetic architecture underlying cancer susceptibility." (PMID 39683528, 2024). "VDR has emerged as a critical element in cancer biology, and its expression and function have been linked to various cancers." (PMID 39268267, 2024). "The SNP in the Cdx2 (Caudal-type homeobox protein 2, which is an intestine-specific transcription factor with a polymorphic binding site in the VDR gene) has been associated with an overall increased risk of cancer." (PMID 39335182, 2024).
cancer (continued). "In humans, we show that vitamin D levels correlate with lower cancer incidence and that hallmarks of VDR activity are associated with better disease outcomes in cancer patients and improved responses to checkpoint blockade immunotherapy." (PMID 38662827, 2024). "High VDR expression was inversely associated with the malignancy of prostate cancer and the risk of cancer-related mortality." (PMID 38230221, 2024). "Fok1 (rs10735810), Bsm1 (rs1544410), Apa1 (rs7975232), Taq1 (rs731236), and Cdx2 (rs11568820) genes are among the most extensively studied VDR SNPs associated with cancer." (PMID 39335182, 2024). "The VDR gene is involved in the regulation of various cellular processes, and its polymorphisms have been linked to the development of multiple cancer types." (PMID 39213223, 2024). "Hamster models exhibited cancer development inhibition with 25(OH)D compound treatment, and human cancer cells showed the presence of the 25(OH)D receptor (VDR), associated with in vitro growth arrest 7-10." (PMID 38817878, 2024). "Although further research is necessary to fully comprehend the role of VDR polymorphisms in different cancers, genetic VDR variations are critical markers used for the selection of better treatment strategies." (PMID 39335182, 2024). "Our results showed that VDR expression was positively correlated with infiltration of cancer associated fibroblasts, macrophages or neutrophils in 20, 12, and 10 types of human tumors respectively." (PMID 38639057, 2024). "VDR polymorphism (Apa1, Cdx2, and Taq1) is associated with an increased risk of developing various cancer types, including CRC, BCC, SCC, HCC, head and neck cancers, kidney cancers, and thyroid cancer." (PMID 39335182, 2024). "VDR expression was positively correlated with the infiltration of cancer-associated fibroblasts, macrophages, or neutrophils in 20, 12, and 10 cancer types respectively and this correlation was experimentally validated in PTC." (PMID 38639057, 2024). "VDR polymorphism plays an equally important role, with impact on cancer risk, evolution, and even prognosis value." (PMID 39766100, 2024). "A single nucleotide polymorphism in the vitamin D receptor affects development or progression of cancer and disease outcome further confirming the role of vitamin D in cancer." (PMID 39456696, 2024). "Of note, while VDR was mostly upregulated among cancer types, higher expression of VDR is suggested to exert an anti‐tumorigenic effect and associated with favorable prognosis in multiple types of cancer." (PMID 37888486, 2023). "Nevertheless, many studies on infectious diseases and cancer agree that the hypermethylation of the VDR promoter is associated with reduced VDR expression levels." (PMID 38203278, 2023). "Cancer risk assessment included circulating calcidiol plasma/serum concentrations, vitamin D intake, the presence of the VDR gene polymorphism, and genes involved in the vitamin D metabolism pathway." (PMID 37299554, 2023). "VDR polymorphisms have been described as being correlated with cancer risk, and for CRC, the BsmI polymorphism has consistently been reported to be associated with a reduced CRC risk." (PMID 37371861, 2023). "Since genetic and epigenetic changes can influence the risk of developing cancer, many studies have been focused on the epigenetic signatures of the VDR gene." (PMID 38203278, 2023). "Although vitamin D/VDR is an active topic in cancer research, the mechanism underlying host-microbiome interactions in tumorigenesis is incompletely understood." (PMID 37074210, 2023). "Numerous studies indicate that there is a relationship between VDR polymorphism and the development of cancer." (PMID 35053549, 2022).
cancer (continued). "Studies have shown that the longer form of the VDR protein has lower transcriptional activity, reducing the anticancer properties of calcitriol, and leading to increased cancer susceptibility." (PMID 36440356, 2022). "The association between VDR SNPs and cancer risk was shown among others in the case of breast, keratinocyte, colorectal ovarian, or lung malignancies." (PMID 36362448, 2022). "More than 60 VDR SNPs, located in the promoter regions of exons 2–9, have been linked to the occurrence and prognosis of cancer." (PMID 36440356, 2022). "In a comprehensive meta-analysis in 2014, they collected data regarding the VDR and its role in cancer risk." (PMID 36312675, 2022). "This study was motivated by the two reports demonstrating that VDR signalling reprograms CAFs, thus diminishing their cancer-promoting role in PDAC, and is associated with better clinical outcomes in CRC." (PMID 36424598, 2022). "The SNPs rs2228570 and rs1544410 in exon 2 and intron 8 of the VDR gene, respectively, have been found to influence the risk of cancer and other disorders." (PMID 36017197, 2022). "Activated VDR regulates several of the genes involved in a wide range of cellular functions and processes, and low vitamin D levels have been associated with cancer in humans." (PMID 35884356, 2022). "The VDR polymorphisms must be considered when assessing the efficacy of vitamin D in counteracting cancer risk in a given population." (PMID 35807746, 2022). "Epigenetic changes, such as increased methylation of the VDR resulting in decreased expression are associated with several cancers and infections." (PMID 36246903, 2022). "According to the findings, increased VDR expression in childhood solid tumor cells is linked to a favorable prognosis, i.e., a lower chance of cancer death." (PMID 35884356, 2022). "The effect of disease stages on the association of VDR mRNA enrichmentswith decreased mortalities in cancer patients was analyzed." (PMID 35404047, 2022). "Few studies to date have investigated the associations of genetic variations of the VDR or vitamin D pathway genetic variants and cancer outcomes." (PMID 35996514, 2022). "Vitamin D receptor (VDR) gene polymorphism is considered to be an important cause of cancer development." (PMID 36440356, 2022). "In the development of cancer, both genetic (mutations, polymorphisms) and epigenetic modifications occur that can lead to changes in the VDR protein level or its function." (PMID 36362448, 2022). "The combination of vitamin D intake and high physical activity increased methylation of genes linked to regulation of vitamin D receptor pathway, the Wnt pathway and general cancer processes." (PMID 35879377, 2022). "Clearly, the action of VDR agonists on fibroblasts associated with distinct human cancers is a highly interesting, open line of research." (PMID 35406059, 2022). "For instance, one study found some VDR polymorphisms to modify the association of vitamin D supplementation with the risk of a specific type of cancer." (PMID 33920959, 2021). "It should also be underlined that many types of cancer cells present alterations in vitamin D metabolism and action as a result of Vitamin D Receptor (VDR) and CYP27B1 expression dysregulation." (PMID 34208589, 2021). "Vitamin D supplementation has also caused a lot of interest in recent years in relation to cancer prevention because of the vitamin’s anti-inflammatory and immunomodulatory properties and the presence of Vitamin D Receptor (VDR) in most human organs." (PMID 34501487, 2021). "Taken together, decreased expression of VDR is a distinct feature of cancer cells and is associated with the reduced action of vitamin D." (PMID 34208589, 2021). "The VDR gene is located on chromosome 12q12-14, and several single nucleotide polymorphisms (SNPs) have been investigated for cancer associations." (PMID 33917614, 2021).
cancer (continued). "Characteristics of case–control studies on VDR −FokI and −TaqI and −BsmI polymorphisms and cancer risk included in the meta-analysis." (PMID 33732250, 2021). "All of the four VDR polymorphisms were revealed as significant among cancer individuals with the following homozygous mutant genotypes: aa, bb, ff, and tt." (PMID 33440610, 2021). "The VDR is expressed in PSCs, HSCs, and in cancer associated fibroblasts (CAFs) derived from these cells." (PMID 33868174, 2021). "VDR is rarely mutated in cancers, albeit can be disabled by aberrant histone deacetylation and methylation of its gene." (PMID 34638264, 2021). "VDR activation suppresses pro-fibrotic and pro-tumorigenic properties of cancer associated fibroblasts (CAFs)." (PMID 33868174, 2021). "Vitamin D3 exerts significant control over normal cellular metabolism via plasma membranes ion channels and via VDR genes located near autoimmune and cancer-associated genes." (PMID 33419149, 2021). "The single nucleotide polymorphism (SNP) of the VDR gene affects the function of vitamin D, further confirming the role of vitamin D in cancer progression." (PMID 33732250, 2021). "Previous studies with human tissues highlighted that the higher expression of VDR in tumors was associated with less aggressive cancer and a low risk of cancer related deaths." (PMID 34199743, 2021). "Although these previous studies have shown the positive role of VDR in patient prognosis, VDR has also been found to be associated with increased cancer risk, indicating the controversial role of VDR." (PMID 33928081, 2021). "The detection of higher frequencies of the VDR polymorphisms in CRC patients highlights the role of these polymorphisms in cancer development and progression." (PMID 32471257, 2020). "In line with the antitumor effects of 1,25(OH)2D3 observed in several neoplasias, high VDR expression in human cancer is usually a hallmark of good prognosis." (PMID 33227961, 2020). "Analysis of the OS revealed that VDR expression in primary cancers was associated with longer overall survival (mean survival of patients without and with nuclear VDR was 33.6 vs. 48.8 months, respectively)." (PMID 33227893, 2020). "In selective epidermis VDR knockout animals, predisposition to cancer and impaired wound healing has been observed." (PMID 32911795, 2020). "By our group and others, TLR and VDR polymorphisms have been significantly associated with cancer development, progression, and, therefore, patients’ clinical outcome." (PMID 32344707, 2020). "Twelve articles including 26 studies were found that described the connection between VDR polymorphisms and four different cancers (oral, head and neck, esophagus, and lung) and met the inclusion criteria." (PMID 31690771, 2019). "The aim of this study was to determine the role of select vitamin D receptor (VDR) gene polymorphisms as risk factors in tobacco-related cancers." (PMID 31690771, 2019). "Recently, one of the most intensively studied genes in connection to the risk of cancers has been that of the vitamin D receptor." (PMID 31690771, 2019). "A number of studies have investigated the contribution of vitamin D status and VDR gene variants (polymorphisms and mutations) in several types of cancer, including CRC." (PMID 31534963, 2019). "In BC, VDR expression is inversely associated with a higher cancer incidence, disease progression, and worse prognosis." (PMID 31731733, 2019). "The cumulative OR for the “t” allele of the TaqI VDR polymorphism in the tobacco-related cancer group was 0.83 (0.72–0.96 95% CI) and was statistically significant (p-value = 0.0114)." (PMID 31690771, 2019). "Our analysis revealed that there is a correlation between the TaqI polymorphism of VDR and the risk of tobacco-related cancers." (PMID 31690771, 2019). "Results of previous studies indicate that variations in VDR are associated with cancer incidence, mortality and survival." (PMID 31167402, 2019).